ENO3 (enolase 3)
Description:
Enolase that catalyzes the conversion of 2-phosphoglycerate to phosphoenolpyruvate in glycolysis and the reverse reaction in gluconeogenesis. Appears to have a function in striated muscle development and regeneration.
Synonyms: MSE; GSD13
Tractability: Small molecule: it has a high-quality binding pocket. Antibody: its Gene Ontology location is reachable by antibodies, with high confidence; the Human Protein Atlas places it where antibodies can reach. PROTAC: ubiquitination databases record sites on it; its protein half-life has been measured.
Gene: Protein-coding gene on chromosome 17 (4,948,046 to 4,957,132, forward strand). Ensembl gene ENSG00000108515.
Subcellular location: Cytoplasm
Subcellular location (Human Protein Atlas): Cytosol; Plasma membrane
Pathways (Reactome):
Metabolism: Gluconeogenesis; Glycolysis
Gene Ontology:
Molecular function: protein binding; phosphopyruvate hydratase activity; magnesium ion binding
Biological process: canonical glycolysis; gluconeogenesis; glycolytic process
Cellular component: cytosol; extracellular exosome; extracellular region; membrane; plasma membrane; phosphopyruvate hydratase complex; cytoplasm
Genetic constraint (gnomAD): Loss-of-function variants: 46 observed, 49.81 expected, observed/expected ratio (o/e) 0.92, 90% interval 0.73 to 1.18. The upper end of that interval is the gene's LOEUF score, 1.18, which puts it in group 5 of 6, group 1 being the genes least tolerant of losing a copy. Missense variants: 575 observed, 592.55 expected, observed/expected ratio (o/e) 0.97, 90% interval 0.9 to 1.04. Synonymous variants: 223 observed, 238.97 expected, observed/expected ratio (o/e) 0.93, 90% interval 0.84 to 1.04.
Homologues: Orthologues: chimpanzee ENO3 (100% identical), macaque ENO3 (99% identical), dog ENO3 (98% identical), guinea pig ENO3 (98% identical), rat Eno3 (98% identical), mouse Eno3 (98% identical), pig ENO3 (97% identical), tropical clawed frog eno3 (88% identical), zebrafish eno3 (85% identical), rabbit ENO3 (77% identical), Caenorhabditis elegans enol-1 (73% identical), Drosophila melanogaster Eno (73% identical). Paralogues in human: ENO1 (83% identical), ENO2 (83% identical), ENO4 (25% identical).
Diseases named in the same sentence as ENO3 in open-access papers:
ENO3 is named in the same sentence as 45 diseases in open-access papers, as found by Europe PMC text mining. Sharing a sentence is not in itself a finding about the gene and the disease. The quoted sentences say what the papers report.
lung carcinoma (7 papers, 2020 to 2025). "A knockdown of ENO3 expression exhibited a selective anticancer effect in STK11 mutant lung cancer cells." (PMID 34869590, 2021). "For example, previous researches reported that ENO3 was highly expressed in STK11 mutant lung cancer, colorectal cancer, and its ectopic expression correlated with a worse outcome of patients by bioinformatic analysis." (PMID 35004693, 2021). "Recent researchers found the knockdown of ENO3 exhibits anticancer effect in STK11 mutant cells and suggest that ENO3-based targeted therapy might be promising for lung cancer patients harboring STK11 mutations." (PMID 33747908, 2021). "Some studies show that ENO3 has over expression and selective anticancer effect in STK11 Mutant Lung Cancers." (PMID 40464853, 2025). "Secondly, three genes [ArfGAP With Coiled-Coil, Ankyrin Repeat And PH Domains 2 (ACAP2), Enolase3 (ENO3), and prostate stem cell antigen (PSCA)] showed an upregulation in lung cancer tissue, suggesting their role as an oncogene." (PMID 39199663, 2024). "However, we note that research on ENO3 is relatively few, with existing studies mainly focusing on its overexpression and selective anticancer activity in STK11-mutant lung cancer." (PMID 40464853, 2025).
metabolic myopathy (4 papers, 2013 to 2023). A group of rare inherited disorders characterized by a deficiency of enzymes that are involved in metabolic pathways that affect muscles. "Glycogen storage disease type XIII (GSDXIII) is a very rare inherited metabolic myopathy characterized by autosomal‐recessive mutations in the ENO3 gene resulting in muscle β‐enolase deficiency, an enzymatic defect of the distal part of glycolysis." (PMID 31741825, 2019). "ENO3 is a muscle-specific enolase, catalyzing the conversion of 2- phosphoglycerate into 2-phosphoenolpyruvate, whose deficiency has been associated to a metabolic myopathy." (PMID 23469062, 2013).
colon cancer (2 papers, 2021 to 2023). "In the present study, we observed that miR-2467-3p targets ENO3 expression, inhibits the malignant biological behavior of and glycolysis in colon cancer cells, and alleviates the cancer-promoting effects of LINC00174." (PMID 37448887, 2023). "The present study is aimed at determining the mechanism by which LINC00174 regulates ENO3, glycolysis, and inflammation and elucidates its effects on colon cancer." (PMID 37448887, 2023). "The expression of LINC00174 and ENO3 in colon cancer tissues, its relationship with survival rate, and correlation were analyzed using bioinformatic analysis." (PMID 37448887, 2023). "Next, to analyze the mechanism by which LINC00174 promotes colon cancer, TCGA database was used to identify ENO3, which is positively correlated with LINC00174 in colon cancer tissues." (PMID 37448887, 2023). "To date, several sequencing-based studies have reported that ENO3 is involved in glycolysis and colorectal or colon cancer and that elevated ENO3 promotes ATP production or glycolysis under hypoxic conditions." (PMID 37448887, 2023). "This suggests that miR-2467-3p is a key miRNA for LINC00174 in regulating colon cancer and ENO3 protein levels." (PMID 37448887, 2023). "This further suggests that in colon cancer, the increase in LINC00174 expression promotes ENO3 protein levels at the posttranscriptional level by targeting miR-2467-3p, which, in turn, promotes glycolysis and inflammation, thereby promoting colon cancer progression." (PMID 37448887, 2023). "TCGA analysis revealed that ENO3 expression was increased in colon cancer tissues." (PMID 37448887, 2023). "Similar to LINC00174, ENO3 was also overexpressed in colon cancer and related to a poor prognosis." (PMID 37448887, 2023). "Finally, the effects of LINC00174 and/or miR-2467-3p overexpression on colon cancer, ENO3 protein levels, and inflammation were analyzed using a tumor-bearing mice model." (PMID 37448887, 2023). "LINC00174 was positively correlated with ENO3 in colon cancer tissues." (PMID 37448887, 2023). "Using the colon cancer samples in TCGA database, LINC00174 was found to be positively correlated with ENO3 (r = 0.458, P < 0.001)." (PMID 37448887, 2023). "qRT-PCR was performed from RNA extracted from 43 pairs of colon cancer and adjacent normal tissues to observe the relative expression levels of eight GRGs (P4HA1, STC2, CHPF2, PMM2, PGM2, ENO3, PPARGC1A, and PPP2CB)." (PMID 34422808, 2021).
hepatocellular carcinoma (2 papers, 2021 to 2023). A malignant tumor that arises from hepatocytes. "ENO3 is a metalloenzyme that plays a role in glycolysis and also inhibits tumor formation during the development of hepatocellular carcinoma." (PMID 37684969, 2023). "However, the function and underlying modulatory mechanisms of ENO3 in hepatocellular carcinoma (HCC) are still elusive." (PMID 35004693, 2021). "For example, ENO3 is up-regulated in STK11 mutant pulmonary carcinoma and colorectal carcinoma, while down-regulated in pancreatic cancer and hepatocellular carcinomas." (PMID 35004693, 2021).
pancreatic cancer (2 papers, 2012 to 2022). "Furthermore, the qPCR results indicated the mRNA expression levels of JMJD6, ANKZF1, CITED2, and ENO3 was obviously decreased in pancreatic cancer cells versus the normal pancreatic ductal epithelial cells, whereas those of LDHA, TES, and SIAH2 were oppisite." (PMID 35935823, 2022). "Comparing the expression levels between the tissue sections from multiple patients, all pancreatic tumor specimens stained positive for GLUT1, HK2, ENO3, LDHA and PKM2." (PMID 22412968, 2012).
bladder tumor (1 paper, 2022). "Consistently, data from TIMER database manifested that mRNA expression of ENO1, but not ENO2 and ENO3, was upregulated in bladder tumor tissues." (PMID 35836227, 2022).
brain injury (1 paper, 2019). Acute and chronic (see also brain INJURIES, CHRONIC) injuries to the brain, including the cerebral hemispheres, CEREBELLUM, and brain STEM. "It has been reported that Eno3 is upregulated in traumatic brain injury." (PMID 30770755, 2019).
cardiac hypertrophy (1 paper, 2009). "Interestingly, in these hypertensive rats, Eno3 showed a negative correlation with LV mass index, whereas, in our model of mild physical exercise without cardiac hypertrophy, Eno3 gene showed an increased expression in trained rats." (PMID 19643001, 2009).
colitis (1 paper, 2023). Inflammation of the colon. "Overall, kumatakenin alleviated DSS-induced colitis largely by inhibiting epithelial ferroptosis, which was linked to activation of Eno3 and subsequent degradation of IRP1 and homeostasis of cellular iron levels." (PMID 37006994, 2023). "RNA sequencing, qPCR, and pharmacological inhibition assays showed that kumatakenin reduced cellular iron levels and suppressed ferroptosis in epithelial cells from colitis mice at least partially by upregulating expression of enolase (Eno-3)." (PMID 37006994, 2023). "Western blotting and IHC confirmed that Eno3 expression in colitis mice was significantly lower than the vehicle group; this effect was reversed by treatment with kumatakenin." (PMID 37006994, 2023). "Furthermore, the Eno3 inhibitor ENOblock significantly reversed kumatakenin-induced anti-colitis effects, including restoration of mucosal bleeding, vascular patterns and loose stools, restoration of intestinal villi, increased colon length, and decreased DAI score." (PMID 37006994, 2023).
colon adenocarcinoma (1 paper, 2022). "Results showed increased expression of ENO3, MORC2, SUCLG2 and ELOVL6, and decreased expression of CPT2 in all examined colon adenocarcinoma cell lines." (PMID 36568396, 2022). "Moreover, qRT-PCR revealed upregulated expression of ENO3, MORC2, SUCLG2 and ELOVL6, and downregulated expression of CPT2 in all examined colon adenocarcinoma cell lines." (PMID 36568396, 2022).
dental fluorosis (1 paper, 2022). A condition that results from excessive fluoride ingestion during tooth development, resulting in tooth discoloration ranging from white streaks to brown stains and cracks or pits in the tooth enamel. "The KGML network diagram showed that the proteins (LDHA, ENO3, GPI, and TPI1) enriched in the HIF-1 and glycolysis/gluconeogenesis pathways have a direct correlation with the formation of dental fluorosis." (PMID 35897842, 2022). "The up-regulation of ENO3, LDHA, TPI1, and GPI implies that the HIF-1 pathway and glycolysis/gluconeogenesis pathway are strengthened in ameloblasts, which affects the energy harvesting of ameloblasts and leads to the formation of dental fluorosis." (PMID 35897842, 2022).
diffuse large B-cell lymphoma (1 paper, 2022). "Correlation with known diffuse large B-cell lymphoma markers showed that high expression of MYC, BCL2, and ENO3 was associated with worse outcome." (PMID 36358737, 2022).
dyslipidemia (1 paper, 2020). "Some of the DE proteins predicted to affect mitochondrial function also cause dyslipidemia, including MECR, CS, ACLY, AOX3, and COX6B1 by RIS, and CYCS, COX6B1, and ENO3 by OLAN." (PMID 33302598, 2020).
endometriosis (1 paper, 2025). The growth of functional endometrial tissue in anatomic sites outside the uterine body. "In the merged dataset, the expression levels of these six genes—DDR2, ENO3, ESM1, NMBR, PRKAB1, and PRPF19—showed significant differences between normal and endometriosis samples (DDR2, p < 0.001; ENO3, p < 0.001; ESM1, p < 0.001; NMBR, p = 0.002; PRKAB1, p < 0.001; PRPF19, p < 0.001)." (PMID 41424583, 2025).
gastric ulcer (1 paper, 2022). An ulcerated lesion in the mucosal surface of the stomach. "The significant downregulation of Eno3 in the MD-4 group indicated that pretreatment could prevent gastric ulcers caused by oxidative stress in rats." (PMID 36292625, 2022). "This study proved the role of MD-4 in preventing gastric ulcers in experimental animals, and revealed that its mechanism is to reduce oxidative stress by downregulating key genes, such as Eno3." (PMID 36292625, 2022). "Downregulation of Srm, Ryr-1, Eno3, Prkag3, and Eef1a2 genes involved in regulating arginine and proline metabolism, calcium signaling pathway, HIF-1 signaling pathway, oxytocin signaling pathway, and legionellosis are possibly involved in MD-4-mediated protection against gastric ulcers." (PMID 36292625, 2022).
hepatic (1 paper, 2023). "This interfered with glucose metabolism by targeting the inhibition of ENO3 expression, which in turn led to the development of hepatic IR." (PMID 37960269, 2023).
liver cancer (1 paper, 2019). An epithelial or non-epithelial malignant neoplasm that arises from the liver. "ENO3 and ESR1 protein were downregulated in liver cancer tissues compared with normal tissues." (PMID 31410310, 2019).
lymphoma (1 paper, 2020). A malignant (clonal) proliferation of B- lymphocytes or T- lymphocytes which involves the lymph nodes, bone marrow and/or extranodal sites. "In lymphoma cells, PRDM15 regulates the transcription of key genes involved in two major metabolic axes required for tumor cell survival: PI3K/AKT/mTOR signaling (InsR and Igf1R) and glycolysis (e.g Pkm, Pfkp, Eno3)." (PMID 32665551, 2020).
Myalgia (1 paper, 2025). "Second, APC, ENO3, ACAD9, RNASEH1, FKTN, DYSF, and ATP2A1 are associated with Myalgia." (PMID 40831500, 2025).
non-alcoholic fatty liver disease (1 paper, 2023). "Eno3 has been recently reported to be up-regulated in non-alcoholic fatty liver disease and regulate ferroptosis and lipid accumulation, however, its role in immune reaction has not been studied." (PMID 38143768, 2023).
Obesity (1 paper, 2015). Accumulation of substantial excess body fat. "These enzymes were glucose 6-phosphate isomerase (GPI), triosephosphate isomerase (TPI), enolase (Eno3), lactate dehydrogenase (LDHa), glyoxalase-1 (Glo1) and the mitochondrial DLD, whose expressions were modified by AM251 in hypercaloric diet-induced obesity." (PMID 26671069, 2015).
pancreatic ductal adenocarcinoma (1 paper, 2023). An infiltrating adenocarcinoma that arises from the epithelial cells of the pancreas. "Besides CRC, ENO3 also functions in pancreatic ductal adenocarcinoma (PDAC)." (PMID 36781976, 2023).
preeclampsia (1 paper, 2023). Preeclampsia is a hypertensive disorder of pregnancy that is characterized by new-onset hypertension with proteinuria presenting after 20 weeks of gestation, and depending on mild or severe forms may initially present with severe headache, visual disturbances, and hyperreflexia. "Seven genes (including MKNK1, ARNT, FLT1, SERPINE1, ENO3, LDHA, BCL2) were screen out to build potential diagnostic model of preeclampsia." (PMID 37020283, 2023). "In summary, our study identified MKNK1, ARNT, FLT1, SERPINE1, ENO3, LDHA, BCL2 out of HIF1-signaling pathway as novel diagnostic biomarkers for preeclampsia patients, and a diagnostic signature based on these genes is constructed for preeclampsia." (PMID 37020283, 2023).
retinoblastoma (1 paper, 2022). A malignant tumor that originates in the nuclear layer of the retina. "Retinoblastoma-derived exosomes are enriched in multiple metabolic enzymes, including enolase 3 (ENO3), galactokinase-1 (GALK1), asparagine synthase (ASNS) and saccharopine dehydrogenase (SCCPDH)." (PMID 36588730, 2022).
teratoma (1 paper, 2020). A non-seminomatous germ cell tumor characterized by the presence of various tissues which correspond to the different germinal layers (endoderm, mesoderm, and ectoderm). "The level of mRNAs encoding Pax3 was significantly higher, while the expression of Nfix, Eno3, Mck, Mef2a, and Itga7 was significantly lower in Pax7−/− teratomas, as compared to Pax7+/+ ones." (PMID 32552916, 2020). "The level of mRNAs encoding Pax3 was significantly higher, while the expression of Nfix, Eno3, Mck, Mef2a, and Itga7 was significantly lower in Pax7−/− teratomas, as compared to Pax7+/+ teratomas." (PMID 32552916, 2020).
thyroid follicular carcinomas (1 paper, 2015). "ENO3 is another cancer-related gene, associated to the PAX8-PPARG fusion protein in thyroid follicular carcinomas, and upstream regulation of PPARs and PPAR-related pathways was detected in the present study." (PMID 26492889, 2015).
tumor (15 papers, 2012 to 2025). "Cells overexpressed ENO3 exhibited much lower tumor growth rates than vector cells with a dramatic reduction in the tumor volume." (PMID 35004693, 2021). "Taken together, our study uncovered that ENO3 acted as a tumor inhibitor in HCC development and implied ENO3 as a promising candidate for HCC treatment." (PMID 35004693, 2021). "Differential expression of proteins was observed between stromal and tumor cells for ENO3, GLUT1, HK2, IDH3A, LDHA and PKM2." (PMID 22412968, 2012). "Notably, the expression of the creatine kinase genes Ckm and Ckmt2 and the muscle‐specific glycolytic enzyme Eno3 was also reduced, implicating that the energy metabolism supporting muscle contraction was negatively impacted by tumours." (PMID 39001644, 2024). "In addition, the regulatory effects of LINC00174 on tumor growth and ENO3 protein levels via miR-2467-3p were confirmed via animal experiments." (PMID 37448887, 2023). "Moreover, LINC00174 overexpression reversed the inhibitory effects of ENO3 protein levels on tumor tissues via miR-2467-3p." (PMID 37448887, 2023). "Moreover, using animal experiments, the regulatory effects of LINC00174 on tumor growth, ENO3 protein levels, and inflammation via miR-2467-3p were confirmed." (PMID 37448887, 2023). "And the expression levels of MORC2, ELOVL3 and ENO3 were significantly increased in tumor tissues." (PMID 36568396, 2022). "In contrast, the mRNA expression of ENO3 and CD36was markedly down-regulated in tumor tissues." (PMID 33226369, 2020). "Our study provides some confirmation of prior findings and expands on them by suggesting that ENO3 highly expressed in LUAD under hypoxic conditions, potentially contributing to tumor metabolism and immune regulation within the TME." (PMID 40464853, 2025). "Furthermore, ENO3 may have a unique function in promoting glycolysis in tumor cells." (PMID 37448887, 2023). "ENO3, FBP1, FBP2, GPD1, and ALDOB were all glycolytic pathway-related proteins with inhibitory effects on tumor." (PMID 33200655, 2020). "All seven glucose metabolism-related proteins were downregulated in SBP1 induced-tumor tissue, including GAA, GAPDH, ALDH2, Thioredoxin, ENO3, UGDH and Lumican." (PMID 25974208, 2015).